BACE1 (beta-secretase 1)
Diseases named in the same sentence as BACE1 in open-access papers (continued):
Sharing a sentence is not in itself a finding about the gene and the disease.
Alzheimer disease (continued). "Furthermore, BACE1 is known as rate-limiting enzyme for Aβ formation leading to Alzheimer's disease, making it a good target for drug design to treat Alzheimer's disease." (PMID 25254246, 2014). "In contrast, one study reported that metformin could deregulateβ-secretase (BACE1) promoter activity and induce more than twice the normal production ofβ-amyloid peptide (Aβ), the protein that forms toxic brain plaques in Alzheimer's disease (AD)." (PMID 24782665, 2014). "Furthermore, beta-amyloid precursor protein cleavage enzyme 1 (BACE1), a member of aspartyl protease family, is known to play an important role in the cellular pathways leading to Alzheimer's disease." (PMID 25254246, 2014). "Beta-amyloid precursor protein cleaving enzyme 1 (BACE1), a major neuronal β-secretase critical for the formation of β-amyloid (Aβ) peptide, is considered one of the key therapeutic targets that can prevent the progression of Alzheimer’s disease (AD)." (PMID 24637500, 2014). "β-site amyloid precursor protein cleaving enzyme 1 (BACE1) is the β-secretase enzyme required for the production of the neurotoxic β-amyloid (Aβ) peptide that is widely considered to have a crucial early role in the etiology of Alzheimer’s disease (AD)." (PMID 25621019, 2014). "The β-site APP cleaving enzyme 1 (BACE1) is an important target for causing Alzheimer's disease (AD), due to the brain deposition peptide amyloid beta (Aβ) require cleavages of amyloid precursor protein (APP) by BACE1 and γ-secretase, but treatments of AD still have side effect in recent therapy." (PMID 24900984, 2014). "Moreover, PCSK9 has been shown to regulate levels of BACE1, one of the enzymes that cleaves APP to form the Aβ peptide associated with Alzheimer disease." (PMID 23430252, 2013). "In addition, many of the studies have focused on miRNA targets related to already known disease genes, such as LRRK2 in Parkinson's disease and BACE1 in Alzheimer's disease." (PMID 24133413, 2013). "This may be the case for the beta-site amyloid precursor protein-cleaving enzyme 1 (BACE1) gene, which encodes an enzyme involved in the production of beta-amyloid plaques in the brain of patients with Alzheimer's disease (AD)." (PMID 23950723, 2013). "BACE1 plays a critical role in the pathogenesis of Alzheimer’s disease." (PMID 23613819, 2013). "We believe that the two low-micromolar inhibitors described here may represent a starting point for finding potent and selective molecules capable of preventing BACE-1 activity for the treatment of Alzheimer’s disease." (PMID 22701601, 2012). "β-Secretase (BACE1) is a major drug target for combating Alzheimer's disease (AD)." (PMID 22903875, 2012). "In this research, the tryptoline core compound previously reported as BACE1 inhibitor was modified in silico to possess multi-modes of action for the treatment of Alzheimer’s disease i.e., anti-amyloid aggregation, metal chelating and radical scavenging action." (PMID 22781443, 2012). "Interestingly, miR-107 has been shown to be significantly down-regulated in Alzheimer's disease and one of its targets, BACE1, was found to be increased." (PMID 21625387, 2011). "In addition miR-29a/b was shown to be involved in BACE-1 expression in patients with Alzheimer's disease." (PMID 21373187, 2011). "Alzheimer's disease (AD) is caused by accumulation of Aβ, which is produced through sequential cleavage of β-amyloid precursor protein (APP) by the β-site APP cleaving enzyme (BACE1) and γ-secretase." (PMID 21829577, 2011). "Currently, BACE1 inhibitors are in development for the treatment of Alzheimer's disease." (PMID 20041192, 2009). "Because few substrates of BACE1 have been identified and BACE1 knockout mice were initially described as having no phenotype, chronic inhibition of BACE1 has been proposed as a potentially attractive therapy for Alzheimer's disease." (PMID 20041192, 2009).
Alzheimer disease (continued). "Let us take the potential interaction in risk of Alzheimer's disease (AD) between the ε4 allele of apolipoprotein E (APOE4) and the GG genotype of the C/G polymorphism (rs638405) in exon 5 of the β-site APP-cleaving enzyme (BACE1)." (PMID 19527493, 2009). "Highlights of the conference included reports on brain imaging, the discovery of mutations in the progranulin gene that cause frontotemporal dementia, the finding that neuregulin-1 is a substrate for BACE1 and new interest in the connection between Alzheimer's disease and metabolic syndromes." (PMID 16956414, 2006). "In addition to BACE1, our study utilizing multi-target drug modeling and surface plasmon resonance experiments identified Aβ 1-42 as a high-affinity target of berberine, suggesting its potential in treating Alzheimer’s disease." (PMID 39944624, 2025). "In addition to superior enhancement of cognitive performance and restoration of neurotransmitter balance, S/L treatment more effectively reduced oxidative stress and neuroinflammatory indices and robustly downregulated Alzheimer’s disease–specific biomarkers, including BACE1, Aβ, and p-Tau." (PMID 41471381, 2025). "Additionally, we conducted ADME (Absorption, Distribution, Metabolism, and Excretion) and toxicity (T) analyses of the selected top dual inhibitors to find dual inhibitors of AChE and BACE1 for developing lead compounds with fewer side effects and more potency against Alzheimer’s disease." (PMID 40560959, 2025). "Alzheimer’s disease (AD) is pathologically characterized by extracellular plaques composed of amyloid beta (Aβ) proteins that are produced by amyloidogenic cleavage of Aβ-precursor protein (AβPP), a process controlled by the rate-limiting beta-site AβPP cleaving enzyme (BACE-1)." (PMID 40313365, 2025). "Thus, this study identifies BACE2 as a modulator of lymphangiogenic VEGFR3 signaling and demonstrates the utility of sVEGFR3 as a pharmacodynamic plasma marker for BACE2 activity in vivo, a prerequisite for developing BACE1-selective inhibitors for safer prevention of Alzheimer’s disease." (PMID 38888964, 2024). "Alzheimer’s disease (AD) is a neurodegenerative disorder associated with the dysregulation of several key enzymes, including acetylcholinesterase (AChE), cyclooxygenase-2 (COX-2), glycogen synthase kinase 3β (GSK-3β), β-site amyloid precursor protein cleaving enzyme 1 (BACE-1), and caspase-3." (PMID 39598743, 2024). "The protease BACE1 is a major drug target for Alzheimer’s disease, but chronic BACE1 inhibition is associated with non-progressive cognitive worsening that may be caused by modulation of unknown physiological BACE1 substrates." (PMID 36810097, 2023). "BACE1 is also linked to pathophysiological processes, in particular to Alzheimer’s disease where it is a major drug target because it cleaves the amyloid precursor protein (APP) and catalyzes the first step in the generation of the amyloid β peptide, a key pathogenic agent in Alzheimer’s disease." (PMID 34958451, 2022). "The elevated expression of miR-124 in Alzheimer’s disease (AD) was shown to benefit the neurite outgrowth, mitochondria activation, small Aβ oligomer reduction, and beta-site amyloid precursor protein cleaving enzyme 1 (BACE1) in experimental models and patients." (PMID 36140218, 2022). "The BACE1 protein plays an essential role in cognitive, emotional and synaptic functions; however, dysregulation of protein levels leads to higher levels of amyloid-β 1-42 that form the β-amyloid plaques in the brain, which are characteristic of Alzheimer’s disease." (PMID 33946840, 2021). "For a long time, the great potential of coumarin-triazole hybrids in anti-Alzheimer’s disease drug discovery has been well demonstrated by the target-based screening of acetylcholinesterase (AChE), butyrylcholinesterase (BuChE), and β-secretase (BACE1) inhibitors." (PMID 34869223, 2021).
Alzheimer disease (continued). "Moreover, miR-124-3p directly targets beta-secretase 1, which has a crucial role in the formation of beta-amyloid, indicating that miR-124-3p downregulation contributes to the pathologic hallmarks of Alzheimer’s disease." (PMID 32244461, 2020). "BACE1, also called β-amyloid precursor protein cleaving enzyme 1 or β-secretase, is a transmembrane aspartyl protease that has gained significant attention as a crucial protease for the generation of the β-amyloid peptide, a crucial initiator in the pathogenesis of Alzheimer’s disease (AD)." (PMID 32508682, 2020). "In addition, reduced expression of miR-29 family causes several neurodegenerative disorders, including Alzheimer’s disease, Huntington’s disease, and spinocerebellar ataxias, by targeting voltage-dependent anion channel 1 (VDAC1), β-secretase 1 (BACE1) and neuron navigator 3 (NAV3)." (PMID 29495532, 2018). "The aspartyl protease β-site APP cleaving enzyme, BACE1, is the rate-limiting enzyme involved in the production of amyloid-β peptide, which accumulates in both sporadic and familial cases of Alzheimer’s disease and is at the center of gravity of the amyloid cascade hypothesis." (PMID 27853315, 2016). "Because global deletion of Bace1 protected mice from diet-induced diabetes, we hypothesised that neuronal BACE1 may regulate system metabolism in addition to inducing brain pathologies relevant to Alzheimer’s disease." (PMID 27138913, 2016). "Aberrant elevation of BACE1 levels in brains of Alzheimer’s disease (AD) patients may involve Aβ." (PMID 26552445, 2015). "In addition, BACE1 finsertms to play a role in glucose and lipid homoeostasis and may be a link between Alzheimer’s disease and diabetes." (PMID 25961820, 2015). "In-depth analysis of structure and function of BACE1 gene core promoter will greatly advance our understanding the transcriptional mechanisms of TATA-less core promoter and may benefit for developing new strategies in inhibiting BACE1 expression in prevention and treatment of Alzheimer's disease." (PMID 25359283, 2014). "Thus, BACE1 is a key target for candidatedisease-modifying treatment of Alzheimer’s disease." (PMID 25404952, 2014). "Future studies aimed at manipulating of polarized neuronal BACE1 trafficking to assess potential modulation of Aβ production in vivo would be necessary to evaluate if trafficking modulation of BACE1 could serve as a therapeutic strategy in Alzheimer’s disease to reduce cerebral amyloid burden." (PMID 24386896, 2014). "Since BACE1-mediated amyloidogenic cleavage of APP is the rate-limiting step in generation of Aβ peptide, better understanding of the dynamics of APP-BACE1 interaction could help explain cellular mechanisms involved in the early stages of pathogenesis of Alzheimer's disease." (PMID 24932508, 2014). "These classes include products involved in APP signalling and processing (BACE1 and 2 and gamma-secretase components), cholesterol and lipoprotein function, tau function, inflammation, and oxidative stress, all of which are key processes disrupted in the Alzheimer's disease brain." (PMID 21234306, 2010). "Ramalin alleviates Alzheimer's disease pathology by selectively inhibiting HDAC6, reducing BACE1 levels, and suppressing neuroinflammation through downregulation of the NLRP3 inflammasome and iNOS." (PMID 41488470, 2026). "In Alzheimer’s disease studies, RVG peptides expressed together with the exosome membrane surface protein Lamp2b effectively introduced targeted delivery of BACE1 siRNA into the mouse brain, with gene-silencing effects." (PMID 41306963, 2025). "The pathological role of BACE1 in cerebral amyloid angiopathy (CAA) and Alzheimer’s disease has been confirmed in experimental studies." (PMID 39944624, 2025). "In Alzheimer’s disease research, RVG peptide expressed with lamp2b protein on the exosomal surface can introduce the target delivery of BACE1 siRNA into mice brain and demonstrate efficient gene silencing." (PMID 38589859, 2024).
Alzheimer disease (continued). "We began our study with three critical proteins involved in Alzheimer’s Disease—tau, APP, and BACE1." (PMID 38540368, 2024). "Neurotoxic β-amyloid peptides (Aβ) are major drivers of Alzheimer’s disease (AD) and are formed by sequential cleavage of the amyloid precursor protein (APP) by β-secretase (BACE1/2) and γ-secretase, respectively." (PMID 39439934, 2024). "BACE1, an enzyme that cleaves Amyloid Precursor Protein (APP) and produces Amyloid β (Aβ), is a promising target for Alzheimer's Disease (AD) treatment." (PMID 38965280, 2024). "Three of these predicted targets (i.e., APP, BACE1, and MAPT) were found to be highly interacting proteins (i.e., hub proteins) in the constructed Alzheimer’s disease PPI network." (PMID 37367890, 2023). "Overall, we also found other important DEGs, viz., BACE1 and BACE2, which belong to a class of proteases called β-secretases that are extensively studied in Alzheimer’s disease." (PMID 37218885, 2023). "By utilizing existing clinical date from DisGeNET and undergoing protein-protein network analysis on cholesterol metabolism and Alzheimer’s disease, the top target genes selected were GSK3B, BACE1, SREBP2, CYP46A1, ABCA1, and TREM2." (PMID 37444065, 2023). "Atabecestat, a potent brain penetrable BACE1 inhibitor that reduces CSF amyloid beta (Aβ), was developed by Janssen Research & Development LLC and Shionogi and Co Ltd as an oral treatment for Alzheimer’s disease (AD)." (PMID 37658353, 2023). "For Alzheimer's disease, miR‐21 attenuates neural inflammation, and miR‐124 regulates beta‐site amyloid precursor protein (APP) cleaving enzyme 1 (BACE1)." (PMID 35716062, 2022). "In the CA1 and CA3 regions of the hippocampus and temporal cortex, genes related to Alzheimer’s disease, such as the amyloid protein precursor (APP), β-secretase (BACE1), presenilin 1 (PSEN1) and 2 (PSEN2), are deregulated by ischemia." (PMID 35741821, 2022). "ADAM17, BACE1, CAPN1, CDK5, EIF2AK3, GRIN2B, and GSK3B were enriched in the Alzheimer disease pathway (hsa05010)." (PMID 33807157, 2021). "The epigenetic regulation is an important aspect of Alzheimer’s disease as the expression level of many key proteins such as APP, BACE1, Presenilins and ApoE are known to be under epigenetic regulation." (PMID 33962636, 2021). "Inhibition of BACE1 is one of the possible treatment options for Alzheimer’s disease and RTN3A1 inhibits BACE1 via two mechanisms." (PMID 34796010, 2021). "BACE inhibitors, which decrease BACE1 (β-secretase 1) cleavage of the amyloid precursor protein, are a potential treatment for Alzheimer’s disease." (PMID 34302009, 2021). "Its close homolog BACE1 (β-site APP-cleaving enzyme 1) is highly expressed in the brain and responsible for initiating the amyloid cascade in Alzheimer's disease (AD)." (PMID 34015524, 2021). "Remarkably, one of these genes, seizure related 6 homolog like is one of the physiological substrate of the β-secretase BACE1 (β-site APP cleaving enzyme), involved in the pathophysiology of Alzheimer’s disease and a drug target." (PMID 32742258, 2020). "BACE1 is the first enzyme involved in APP processing, thus it is a strong therapeutic target candidate for Alzheimer’s disease." (PMID 31882662, 2019). "In fact, the miR-124 level in the brain of patients with Alzheimer’s disease is down-regulated, in parallel to the increase in expression of beta-site expression APP-cleaving enzyme 1 (BACE1)." (PMID 30934805, 2019). "Microvesicles in the CSF of 15 patients with Alzheimer’s disease and 15 controls were analyzed by flow cytometry regarding the levels of CD3, CD4, CD45, CD64, BACE1, Aβ, APP and tau." (PMID 31068645, 2019). "β-site APP-cleaving enzyme 1 (BACE1) initiates amyloid precursor protein (APP) cleavage and β-amyloid (Aβ) production, a critical step in the pathogenesis of Alzheimer’s disease (AD)." (PMID 31108937, 2019).
Alzheimer disease (continued). "Assessing BACE1 (β-site APP cleaving enzyme 1) knockout mice for general health and neurological function may be useful in predicting risks associated with prolonged pharmacological BACE1 inhibition, a treatment approach currently being developed for Alzheimer’s disease." (PMID 28281673, 2017). "For example, MID1 binds to BACE1 mRNA and induces its translation linking translational regulation by MID1 to Alzheimer's Disease." (PMID 27774050, 2016). "The β-secretase, BACE1, cleaves APP to initiate generation of the β-amyloid peptide, Aβ, that comprises amyloid plaques in Alzheimer’s disease (AD)." (PMID 25567526, 2015). "Thus, BACE1 seems to play an important role in neuronal excitability and is essential for cognitive, emotional, and synaptic functions and BACE1 inhibitors may normalize membrane excitability in Alzheimer’s disease patients with elevated BACE1 activity." (PMID 26321914, 2015). "In patient with Alzheimer’s disease (AD), deposition of amyloid-beta Aβ, a proteolytic cleavage of amyloid precursor protein (APP) by β-secretase/BACE1, forms senile plaque in the brain." (PMID 25773675, 2015). "β-site APP cleaving enzyme 1 (BACE1) initiates APP cleavage, which has been reported to be an inducer of tau pathology by altering proteasome functions in Alzheimer’s disease (AD)." (PMID 26778963, 2015). "Proteolytic processing of amyloid-β precursor protein (APP) by beta-site APP cleaving enzyme 1 (BACE1) is the initial step in the production of amyloid beta (Aβ), which accumulates in senile plaques in Alzheimer’s disease (AD)." (PMID 26053850, 2015). "β-site APP cleaving enzyme 1 (BACE1) cleaves β-amyloid precursor protein (APP) to initiate the production of β-amyloid (Aβ), the prime culprit in Alzheimer’s disease (AD)." (PMID 22709416, 2012). "The β site APP cleaving enzyme 1 (BACE1) is the rate-limiting β-secretase enzyme in the amyloidogenic processing of APP and Aβ formation, and therefore it has a prominent role in Alzheimer’s disease (AD) pathology." (PMID 22952813, 2012). "The voltage-gated sodium channel β2 subunit (Navβ2) is a physiological substrate of BACE1 (β-site APP cleaving enzyme) and γ-secretase, two proteolytic enzymes central to Alzheimer's disease pathogenesis." (PMID 21182789, 2010). "Despite emerging evidence linking Alzheimer’s disease with epilepsy, there is a notable absence of studies examining the modulation of BACE-1 in individuals with epilepsy." (PMID 40291844, 2025). "Thus, a single, once in a lifetime transient composite therapy with concurrently administered BACE1 and/or BACE 2 activators and ISR inhibitors can stop for life the progression of conventional Alzheimer’s disease and preclude its recurrence." (PMID 40362488, 2025). "(DE), obtained from a non-optimized extraction condition exhibited anti-Alzheimer’s disease (AD) properties through the inhibition of a rate-limiting enzyme in amyloid peptide formation, β-secretase-1 (BACE-1)." (PMID 38792065, 2024). "It is important to note that the GPCRs in the right cluster relate to APP and BACE1, which, while not ideal targets themselves, are well-known in their involvement with Alzheimer’s disease." (PMID 38276010, 2024). "Additionally, an in vivo study reported the use of a linear polyethyleneimine (LPEI)-g-polyethylene glycol (PEG) copolymer-based micellar nanoparticle system to deliver siRNA targeting BACE1 and APP, two key therapeutic targets in Alzheimer’s disease." (PMID 39204177, 2024). "Alzheimer’s disease (AD) is characterized by the presence of tau protein inclusions and amyloid beta (Aβ) plaques in the brain, with Aβ peptides generated by cleavage of the amyloid precursor protein (APP) by BACE1 and γ-secretase." (PMID 37269953, 2023). "Remarkably, the experiments with mouse models for Alzheimer’s disease revealed the complete absence of amyloid beta when BACE1 was silenced." (PMID 37834241, 2023).